SMIM12 (small integral membrane protein 12)
Synonyms: C1orf212; FLJ90372
Tractability: Antibody: UniProt predicts a signal peptide or a membrane-spanning region. PROTAC: ubiquitination databases record sites on it; its protein half-life has been measured.
Gene: Protein-coding gene on chromosome 1 (34,712,737 to 34,859,805, reverse strand). Ensembl gene ENSG00000163866.
Subcellular location: Membrane
Subcellular location (Human Protein Atlas): Mitochondria
Gene Ontology:
Molecular function: protein binding
Cellular component: mitochondrion; membrane
Genetic constraint (gnomAD): Loss-of-function variants: 5 observed, 6.66 expected, observed/expected ratio (o/e) 0.75, 90% interval 0.39 to 1.54. That is too few expected variants to judge how well the gene tolerates losing a copy. Missense variants: 103 observed, 125.92 expected, observed/expected ratio (o/e) 0.82, 90% interval 0.7 to 0.96. Synonymous variants: 51 observed, 50.69 expected, observed/expected ratio (o/e) 1.01, 90% interval 0.8 to 1.27.
Homologues: Orthologues: chimpanzee SMIM12 (100% identical), pig SMIM12 (99% identical), guinea pig SMIM12 (97% identical), rat Smim12 (97% identical), mouse Smim12 (96% identical), zebrafish smim12 (74% identical), tropical clawed frog smim12 (72% identical), Drosophila melanogaster CG34228 (36% identical).
Diseases named in the same sentence as SMIM12 in open-access papers:
SMIM12 is named in the same sentence as 1 disease in open-access papers, as found by Europe PMC text mining. Sharing a sentence is not in itself a finding about the gene and the disease. The quoted sentences say what the papers report.
Obesity (1 paper, 2022). Accumulation of substantial excess body fat. "Comparing the body weight of AAV-injected Sim1-cre mice versus AAV-injected wild-type littermates, we found that overexpression of Snca and Igsf8 caused an exacerbation of HFD-induced obesity, whereas overexpression of Spata2, Pole4, Fndc4, Smim12, or Arrb1 had no impact on body weight." (PMID 36175420, 2022).